MMP3 (matrix metallopeptidase 3)
Diseases named in the same sentence as MMP3 in open-access papers (continued):
Sharing a sentence is not in itself a finding about the gene and the disease.
hip osteoarthritis (1 paper, 2023). "Masuhara K found that local and plasma MMP-3 and MMP-9 levels were significantly elevated in patients with rapidly destructive hip osteoarthritis, and he attributed the elevated blood levels to a large amount of MMP-9 produced in the synovial tissue of the hip." (PMID 36991363, 2023).
Hutchinson-Gilford progeria syndrome (1 paper, 2016). "However, in Hutchinson-Gilford progeria syndrome, there is a progressive loss of MMP3 mRNA and protein expression." (PMID 28105936, 2016).
idiopathic pulmonary arterial hypertension (1 paper, 2021). A sporadic form of pulmonary arterial hypertension (PAH) characterized by elevated pulmonary arterial resistance leading to right heart failure. "Lepetit H's study showed that MMP-TIMPs imbalance (increased TIMP-1 and decreased MMP-3) contributed to smooth muscle cell proliferation in idiopathic pulmonary arterial hypertension." (PMID 35284430, 2021).
idiopathic scoliosis (1 paper, 2011). A scoliosis with no known cause. "Regarding the role of MMPs family in idiopathic scoliosis, there are some contradictory findings in the literature about the role of gene variants of IL-6 and MMP-3 and whether MMP-3 and IL-6 promoter polymorphisms constitute important factors for the genetic predisposition to idiopathic scoliosis." (PMID 21554726, 2011).
Impaired glucose tolerance (1 paper, 2024). An abnormal resistance to glucose, i.e., a reduction in the ability to maintain glucose levels in the blood stream within normal limits following oral or intravenous administration of glucose. "This elevation suggested systemic atherosclerosis linked to impaired glucose tolerance.S1–3 On the other hand, serum expression of TNFRSF1A, CXCL4, MIP‐1 γ, MMP‐3, VEGFR2, IGF‐1, HGFR, OPN, and OPG was significantly lower in db/db mice." (PMID 39001701, 2024).
Incisional hernia (1 paper, 2022). An abdominal hernia that occurs at a site of weakness in the abdominal wall resulting from an incompletely-healed surgical wound. "Analysis of fascia from incisional hernia patients showed substantial elevations of MMP3 and MMP9, deregulation of ECM-altering enzymes, and alteration of collagen I/III ratios." (PMID 35439171, 2022).
intracerebral hemorrhage (1 paper, 2024). A cerebrovascular disorder characterized by bleeding into one or both cerebral hemispheres including the basal ganglia and the cerebral cortex. "However, data from experiments using MMP-9 KO and MMP-3 KO mice suggest that MMP-3 contributes to delayed tPA-induced intracerebral hemorrhage more than MMP-9 does." (PMID 39000490, 2024).
intracranial aneurysm (1 paper, 2016). "Recent studies have shown that NF-κB p65 can promote inflammatory changes and regulate MMPs (MMP-1, MMP-2, MMP-3, and MMP-9) transcription participating in the initiation and progression of AAA and intracranial aneurysm (IA)." (PMID 26918963, 2016).
kidney clear cell carcinoma (1 paper, 2019). "This profile likely results in increased destruction and invasion through the basement membrane and may explain why higher expression of MMP-3 correlates with a poorer prognosis in kidney clear cell carcinoma patients." (PMID 31200666, 2019).
kidney tumor (1 paper, 2022). "Our results show that MMP-10 is about three times more active in healthy human kidney than MMP-3 and four times more active in both grades of kidney tumor in comparison to healthy tissue." (PMID 36231910, 2022).
leiomyoma (1 paper, 2021). A well-circumscribed benign smooth muscle neoplasm characterized by the presence of spindle cells with cigar-shaped nuclei, interlacing fascicles, and a whorled pattern. "Seven women with leiomyomas were evaluated, and MMP3 and MMP10 levels were measured." (PMID 33503183, 2021).
leprosy (1 paper, 2013). Leprosy is a chronic infectious disease affecting primarily the skin and peripheral nervous system. "Expression of MMP3, MMP13, CCL22 were seen to be highest in PBMC cultures of healthy contacts as compared to leprosy types." (PMID 23936569, 2013).
leukoaraiosis (1 paper, 2019). "As for CSVD, a brain-autopsy study revealed that microglia/macrophage cells containing MMP-3 were more often present around small perforating arteries and areas of severe white matter damage corresponding to leukoaraiosis." (PMID 31474817, 2019). "A study discovered that microglia/macrophages cells contained MMP-3 were more present around small perforating arteries and areas of severe white matter damage corresponding to leukoaraiosis." (PMID 31474817, 2019).
limb ischemia (1 paper, 2011). A ischemia that involves the limb. "After 3 days of limb ischemia following femoral artery ligation, MMP-2, MMP-3, and MMP-13 were increased in diabetic mice compared to controls, but collagenolysis was decreased, indicating a suppression of the response." (PMID 22214528, 2011).
lupus erythematosus (1 paper, 2019). An autoimmune, connective tissue chronic inflammatory disorder affecting the skin, joints, kidneys, lungs, heart, and the peripheral blood cells. "This is a meta-analysis aimed at systematically reviewing association between serum MMP-3 levels and systematic lupus erythematosus (SLE) activity, which sought to raise interest in MMP-3 as a putative biomarker." (PMID 31396295, 2019).
Lyme neuroborreliosis (1 paper, 2021). "Although we did not examine the CSF response in this study, a number of genes upregulated in the dura mater of infected mice have been reported to be elevated in the CSF of Lyme neuroborreliosis patients including cytokines/chemokines as well as the matrix metalloproteinases MMP3 and MMP9." (PMID 33524035, 2021).
lymphedema (1 paper, 2024). Excess fluid collection in tissues, causing swelling. "Changes in the frequency distribution of MMP2 genotypes in primary and MMP3 in secondary lymphedema are shown." (PMID 39027126, 2024). "Thus, thefrequency of a combined genetic trait represented by a combinationof homozygous VEGF+936 CC: MMP3-1171 5A5A:MMP9-1562 CC among the patients with secondary lymphedema exceeds the frequency of a similar indicator in the controlgroup by more than 3 times (OR = 3.37; p = 0.0110)." (PMID 39027126, 2024).
mandibular hypoplasia (1 paper, 2021). "Later, after analysis of the tissues of the lower jaw of patients with mandibular hypoplasia, researchers confirmed that MMP-3 genetic abnormalities can lead to mandibular hypoplasia." (PMID 34276395, 2021).
migraine (1 paper, 2014). "In contrast, the reduction in the plasma concentrations of MMP-3 found during the early phase of headache migraine attacks suggest that this isoform should be further investigated in migraine sufferers." (PMID 25339863, 2014).
nasal obstruction (1 paper, 2024). "In our study, long-term unilateral nasal obstruction caused nasal septal deviation toward the unobstructed side, hyper divergent facial development including longer molar dental height, and reduced MMP-3 production." (PMID 38297007, 2024). "In LUC-MMP-3 transgenic rats, unilateral nasal obstruction can significantly reduce the MMP-3 signal, which is mainly expressed in the respiratory epithelium." (PMID 38297007, 2024). "This study used MMP-3-LUC transgenic rats for in vivo tracking of long-term expression in the rat nasal region after unilateral nasal obstruction." (PMID 38297007, 2024). "Unilateral nasal obstruction significantly reduced the MMP-3 signal in the nasal region of MMP-3-LUC transgenic rats, which was mainly expressed in the respiratory epithelium." (PMID 38297007, 2024). "The present study used MMP-3-LUC transgenic rats for long-term tracking of MMP-3 expression in the rat nasal region after unilateral nasal obstruction." (PMID 38297007, 2024). "This expression was suppressed after nasal obstruction, even on the non-obstruction side of the experimental group, meaning that the deprivation of airflow results in the down-regulation of MMP-3." (PMID 38297007, 2024).
ocular hypertension (1 paper, 2015). Abnormally high intraocular pressure. "The basal expression pattern of MMP-3 has not been described yet, although a strong increase in MMP-3 mRNA expression in the retina of rats subjected to an ocular hypertension GON model or to optic nerve injury suggests MMP-3 to be an important player during glaucomatous damage." (PMID 26714639, 2015).
oral diseases (1 paper, 2024). "COL6A1 is a type VI collagen component, while MMP3 is involved in matrix degradation in oral diseases." (PMID 39092323, 2024).
Oropharyngeal Cancer (1 paper, 2024). Carcinoma, predominantly squamous cell, arising from the epithelial cells of the oropharynx. "Our own research showed significantly higher levels of both MMP3 and MMP 9 in the serum of patients with EBV positive oropharyngeal cancer compared to EBV negative patients and the control group." (PMID 38473807, 2024).
oropharyngeal squamous cell carcinoma (1 paper, 2024). "The aim of this study was to evaluate the diagnostic usefulness of matrix metalloproteinase 3 (MMP 3) and matrix metalloproteinase 9 (MMP 9) in EBV positive oropharyngeal squamous cell carcinoma (OPSCC) patients." (PMID 38473807, 2024).
ovarian endometriosis (1 paper, 2019). A non-neoplastic disorder characterized by the growth of endometrial tissue in the ovaries. "The eutopic endometrium of women with ovarian endometriosis has been shown to express high levels of MMP-3, which can hydrolyze and inactivate PAI-1, regulating cell-associated plasmin activities." (PMID 31888633, 2019).
parasitemia (1 paper, 2019). "Consistently, mice infected with T. brucei have a high expression of MMP-3 and MMP-12 at the mRNA level, followed by significant parasitemia increases." (PMID 31597256, 2019).
paroxysmal AF (1 paper, 2011). "Matrix metalloproteinase-9 but not MMP-3 was higher in permanent compared to paroxysmal AF group (p < 0.001)." (PMID 22204652, 2011).
pelvic organ prolapse (1 paper, 2013). Abnormal descent of a pelvic organ resulting in the protrusion of the organ beyond its normal anatomical confines. "We speculated that similar mechanisms related to the 1G/2G MMP-1 and 5A/6A MMP-3 SNPs might exist within the pelvic floor connective tissue in women with clinically significant pelvic organ prolapse." (PMID 23108733, 2013).
peripheral nerve injury (1 paper, 2013). Injury to a peripheral nerve. "MMP3 (stromelysin 1) mediates degeneration of the disc by degradation of matrix proteoglycans and collagens and also contributes to neuropathic pain after peripheral nerve injury." (PMID 23522322, 2013).
Peritoneal Fibrosis (1 paper, 2014). Disorder characterized by a wide range of structural changes in PERITONEUM, resulting from fibrogenic or inflammatory processes. "When standardized against TIMP-1 levels, this reflected a significant decrease in the MMP-3/TIMP-1 ratio, which would predict increased matrix deposition and peritoneal fibrosis." (PMID 24412616, 2014).
pneumococcal infection (1 paper, 2018). Infections with bacteria of the species streptococcus pneumoniae. "When we analyzed the expression of these and other MMPs, we observed that the pneumococcal infection indeed induced the expression of MMP‐2, MMP‐3, MMP‐8 and pro‐MMP9 in the respiratory tract of AIRmax mice." (PMID 29119707, 2018). "Conversely, pneumococcal infection did not induce the expression of MMP‐2 and MMP‐3 in AIRmin mice, not even at 48 h post‐challenge, when high numbers of bacteria were observed." (PMID 29119707, 2018).
pneumococcal meningitis (1 paper, 2006). An acute purulent infection of the meninges and subarachnoid space caused by Streptococcus pneumoniae, most prevalent in children and adults over the age of 60. "We have previously documented the transcriptional upregulation of MMP-3 (#95–#97), -9 and -14 in infant rat brain tissue at 22 h after experimental pneumococcal meningitis." (PMID 16749930, 2006).
pneumonia (1 paper, 2024). An acute, acute and chronic, or chronic inflammation focally or diffusely affecting the lung parenchyma, caused by an infection in one or both of the lungs (by bacteria, viruses, fungi, or mycoplasma.). "In a study, Wang and colleagues assessed serum MMP3’s diagnostic and predictive utility in pneumonia patients." (PMID 39727640, 2024). "The findings show that pneumonia patients had considerably greater admission amounts of MMP3, NGAL, and IL-6 than healthy controls." (PMID 39727640, 2024). "Therefore, MMP3 is a useful biomarker for determining the severity of pneumonia and forecasting mortality in those patients." (PMID 39727640, 2024).
polyarticular JIA (1 paper, 2006). "To further elaborate on potential peptide-specific cytokine production, we generated short-term peptide-specific (aggrecan, fibrillin, or MMP-3) T-cell lines of PBMC from five patients with polyarticular JIA." (PMID 17129378, 2006).
primary lymphedema (1 paper, 2024). A congenital condition that results in swelling in the arms or legs, and can occur during adolescence or adulthood. "Data on an increase in the frequency of homozygousMMP2-1306 CC in primary lymphedema and an increase inthe frequency of homozygous MMP3-1171 5A5A in secondarylymphedema were obtained." (PMID 39027126, 2024). "Thus, in primary lymphedema, the most significant correlationsare revealed between MMP2 and the tissue inhibitorTIMP2 levels (OR = 0.703; p < 0.01), whereas the VEGF serumlevel is inversely correlated with the MMP3 serum level(OR = –0.629; p < 0.05)." (PMID 39027126, 2024).
Q fever (1 paper, 2023). A bacterial infection caused by Coxiella burnetii. "It is possible that the overexpression of MMP-3 modulates MMP-9 expression in cells infected by C. burnetii, thereby contributing to the physiopathology of persistent Q fever." (PMID 37446087, 2023).
retinal angioma (1 paper, 2009). "We observed that variants of MMP1 and MMP3 were significant modifiers of RCC risk (and risks of retinal angioma and cerebellar haemangioblastoma) in VHL disease patients." (PMID 19551141, 2009). "In addition, the observation that MMP1 and MMP3 genotypes also appeared to influence retinal angioma and cerebellar haemangioblastoma risks is consistent with our previous report suggesting shared genetic modifiers of retinal angiomatosis, cerebellar haemangioblastomas and RCC risks in VHL disease." (PMID 19551141, 2009). "Our findings suggest that functional SNPs in MMP1/MMP3 can influence susceptibility to RCC in familial (VHL disease) and sporadic patients and that MMP1 rs1799750 and MMP3 rs679620 genotypes can also influence the risk of retinal angioma and cerebellar haemangioblastoma in VHL disease." (PMID 19551141, 2009).
retinal degeneration (1 paper, 2022). Degeneration of the retina. "The studies involving a dietary saffron and a patented saffron show the key role of MMP-3 in the protection against photoreceptor apoptosis in animal models of light-induced retinal degeneration." (PMID 35056157, 2022).
rhegmatogenous retinal detachment (1 paper, 2024). Retinal detachment secondary to retinal tear or break. "Previous studies have observed elevated levels of stromelysin-1 (MMP-3) in the vitreous and subretinal fluid during rhegmatogenous retinal detachment (RRD), findings consistent with our observations in the aqueous humor of ARN patients." (PMID 39723192, 2024).
rheumatoid lung (1 paper, 2018). "Since serum levels of both anti-MMP3 and anti-CCP antibodies were elevated, RA with rheumatoid lung was diagnosed." (PMID 30024562, 2018).
rosacea (1 paper, 2021). A chronic erythematous skin disorder that affects the face. "Angiogenesis is an essential process in rosacea, which is induced by LL-37 from a signal cascade by microorganisms, VEGF, and MMP-3 from mast cells." (PMID 34769465, 2021).
Sciatica (1 paper, 2009). Pain in the lower back and hip radiating in the distribution of the sciatic nerve. "Moreover, the anti-inflammatory agents' impact was observed in active components of both MMP-1 and MMP-3, suggesting that using these drugs could, at least under certain conditions, alter the speed and extent of DH resorption after an episode of sciatica." (PMID 19906289, 2009).
scleritis (1 paper, 2022). Inflammation of the sclera. "In addition, TNF-α elevates the level of MMPs, which may disrupt the balance between MMPs (MMP3 and MMP9) and TIMPs and induce scleritis." (PMID 35756002, 2022).
scleroderma (1 paper, 2020). Scleroderma is a rare autoimmune connective tissue disorder characterized by abnormal hardening of the skin and, sometimes, other organs. "Therefore, it is assumed that the reduced concentration of MMP-3 in the blood of patients with scleroderma may be caused by the participation of other factors." (PMID 32382564, 2020).
senile cataract (1 paper, 2018). A cataract with no obvious cause occurring in persons over 50 years old. "We found that the concentrations of IL-8, MMP-2, MMP-3, MMP-9, TGFβ-1, TGFβ-2, TGFβ-3, SAA, and TNF-α were significantly elevated in JIAU samples compared with the control group (senile cataract patients)." (PMID 29675026, 2018).
Sensorineural hearing impairment (1 paper, 2024). A type of hearing impairment in one or both ears related to an abnormal functionality of the cochlear nerve. "Elevated plasma MMP-3 levels in RA patients with sensorineural hearing impairment are believed to be associated with systemic inflammation and tissue damage." (PMID 39769062, 2024). "Significantly higher levels of MMP-3 in plasma were observed in RA patients developing sensorineural hearing impairment." (PMID 39769062, 2024).
septic arthritis (1 paper, 2022). "The co‐expression and localization levels of MCT4, GLUT1, IL‐1β, NLRP3, MMP3, and p‐NF‐κB increased by the 14‐day timepoint in chondrocytes and immune cells in our in vivo model of septic arthritis." (PMID 36354099, 2022).
skin inflammation (1 paper, 2019). "MMP-3 (stromelysin-1) exhibits multiple functions in development, inflammation, cancer, wound repair, skin inflammation through proteolyses on cytokines, chemokines, cell surface proteins, extracellular matrices, growth factors, proMMPs, and protease inhibitors." (PMID 31297118, 2019).
sleep disorder (1 paper, 2022). A change from the patient's baseline sleeping pattern, in the hours slept and/or an alteration/dysfunction in the stages of sleep. "This may explain the correlation between MMP3 levels and sleep disorders in PD patients." (PMID 36072482, 2022). "The levels of MMP3 and MMP9 can be used to evaluate sleep disorders and cognitive function in PD patients, respectively." (PMID 36072482, 2022). "After subgroup analysis, sleep disorders were higher than non-sleep disorders, but the difference was not significant, which may be related to the different levels of MMP3 compensation in advanced-stage PD patients." (PMID 36072482, 2022).
small cell lung carcinoma (1 paper, 2020). Small cell lung cancer (SCLC) is a highly aggressive malignant neoplasm, accounting for 10-15% of lung cancer cases, characterized byrapid growth, and early metastasis. "GSEA analysis showed that the MMP1, MMP3, and MMP10 high-expression groups participated in tumor-related ECM receptor interaction, small cell lung cancer, and other pathways." (PMID 32636440, 2020).